SMYD5 (SMYD family member 5)
Description:
Protein-lysine N-trimethyltransferase that specifically catalyzes trimethylation of 'Lys-22' of the RPL40/eL40 subunit of the 60S ribosome, thereby promoting translation elongation and protein synthesis. May also act as a histone methyltransferase in the context of histone octamers, but not on nucleosome substrates: trimethylates 'Lys-36' of histone H3 and 'Lys-20' of histone H4 to form H3K36me3 and H4K20me3, respectively (By similarity). The histone methyltransferase activity, which is independent of its SET domain, is however unsure in vivo. In association with the NCoR corepressor complex, involved in the repression of toll-like receptor 4 (TLR4)-target inflammatory genes in macrophages, possibly by catalyzing the formation of H4K20me3 at the gene promoters (By similarity). Plays an important role in embryonic stem (ES) cell self-renewal and differentiation (By similarity). Maintains genome stability of ES cells during differentiation through regulation of heterochromatin formation and repression of endogenous repetitive DNA elements by promoting H4K20me3 marks. Acts as a regulator of the hypothermia response: its degradation in response to mild hypothermia relieves the formation of H3K36me3 at gene promoters, allowing expression of the neuroprotective gene SP1 (By similarity).
Synonyms: RAI15; RRG1; NN8-4AG; ZMYND23
Tractability: PROTAC: UniProt records ubiquitination sites on it; ubiquitination databases record sites on it; its protein half-life has been measured.
Target class: Enzyme; Transferase
Gene: Protein-coding gene on chromosome 2 (73,214,222 to 73,227,229, forward strand). Ensembl gene ENSG00000135632.
Subcellular location: Cytoplasm
Subcellular location (Human Protein Atlas): Nucleoplasm
Gene Ontology:
Molecular function: protein binding; protein-lysine N-methyltransferase activity; histone H3K36 trimethyltransferase activity; histone H4K20 methyltransferase activity; histone H4K20 trimethyltransferase activity
Biological process: positive regulation of cytoplasmic translational elongation; regulation of stem cell differentiation; transposable element silencing by heterochromatin formation; negative regulation of gene expression, epigenetic; regulation of stem cell division
Cellular component: cytoplasm
Genetic constraint (gnomAD): Loss-of-function variants: 30 observed, 48.78 expected, observed/expected ratio (o/e) 0.62, 90% interval 0.46 to 0.83. The upper end of that interval is the gene's LOEUF score, 0.83, which puts it in group 3 of 6, group 1 being the genes least tolerant of losing a copy. Missense variants: 422 observed, 505.61 expected, observed/expected ratio (o/e) 0.83, 90% interval 0.77 to 0.9. Synonymous variants: 179 observed, 187.1 expected, observed/expected ratio (o/e) 0.96, 90% interval 0.85 to 1.08.
Homologues: Orthologues: macaque SMYD5 (99% identical), chimpanzee SMYD5 (99% identical), rabbit SMYD5 (99% identical), dog SMYD5 (97% identical), guinea pig SMYD5 (96% identical), pig SMYD5 (96% identical), rat Smyd5 (94% identical), mouse Smyd5 (90% identical), tropical clawed frog smyd5 (80% identical), zebrafish smyd5 (73% identical), Drosophila melanogaster Smyd5 (44% identical), Drosophila melanogaster SmydA-7 (17% identical). Paralogues in human: SMYD3 (21% identical), SMYD2 (21% identical), SMYD4 (21% identical), SMYD1 (19% identical), ZMYND15 (13% identical).
Diseases named in the same sentence as SMYD5 in open-access papers:
SMYD5 is named in the same sentence as 29 diseases in open-access papers, as found by Europe PMC text mining. Sharing a sentence is not in itself a finding about the gene and the disease. The quoted sentences say what the papers report.
breast carcinoma (4 papers, 2016 to 2025). "SMYD5 was identified to be critical in cancer metastasis in breast cancer cells during lung colonization." (PMID 29487338, 2018). "Moreover, the histone methyltransferase Smyd5 maintains breast cancer dormancy, and similarly the histone methylation inhibitor 5-azacytidine facilities maintenance in breast cancer and head and neck squamous cell carcinoma (HNSCC)." (PMID 41091336, 2025). "However, SMYD5 was identified to be critical in cancer metastasis in breast cancer cells during lung colonisation." (PMID 27377701, 2016).
hepatocellular carcinoma (3 papers, 2024). A malignant tumor that arises from hepatocytes. "In hepatocellular carcinoma cell lines, SMYD5 knockdown suppressed cell migration and invasion and enhanced paclitaxel sensitivity." (PMID 38723947, 2024). "In cancers, SMYD5 is overexpressed in gastric cancer and hepatocellular carcinoma." (PMID 38723947, 2024). "Interestingly, silencing SMYD5 also increases the sensitivity of hepatocellular carcinoma cells to paclitaxel, suggesting a potential role for SMYD5 in chemoresistance mechanisms." (PMID 39482529, 2024). "Furthermore, functional experiments revealed that SMYD5 downregulation reduces the proliferation, migration, and invasion of hepatocellular carcinoma cells." (PMID 39482529, 2024). "SMYD5 and RPL40 K22me3 are upregulated in hepatocellular carcinoma (HCC) and negatively correlated with patient prognosis." (PMID 39103523, 2024).
lung carcinoma (3 papers, 2023 to 2024). "In other words, the decrease in cell migration and invasion observed with SMYD5 knockdown was linked to the increased expression of SH2B3 in lung cancer." (PMID 38723947, 2024). "The overexpression of SMYD5 in lung cancer cells was found to contribute to cell migration and invasion by directly regulating the expression of the SH2B3 gene through controlled trimethylation of H4K20." (PMID 38723947, 2024). "In conclusion, we identified SMYD5 overexpression in lung cancer with TCGA data portal and immunohistochemical analysis." (PMID 38723947, 2024). "In the cancer genome atlas program (TCGA) portal, SMYD5 was overexpressed in 2 types of lung cancer (lung adenocarcinoma and lung squamous cell carcinoma) samples compared to normal samples." (PMID 38723947, 2024). "In colon and lung cancer cells, SMYD5 maintains chromosomal integrity by regulating heterochromatin and repressing endogenous repetitive DNA elements during cell differentiation." (PMID 36816359, 2023). "Thus, in further studies, ChIP-seq and ATAC-seq analyses will be performed to verify metastasis-related genes related to SMYD5 in the context of lung cancer metastasis." (PMID 38723947, 2024). "In this study, we investigated the novel role of SMYD5 in lung cancer metastasis." (PMID 38723947, 2024). "Therefore, our results suggest that SMYD family members (specifically SMYD2 and SMYD5) are important factors in lung cancer metastasis." (PMID 38723947, 2024). "Based on these findings, we propose that SMYD5 could serve as a potential therapeutic target for lung cancer treatment and that cotreatment with an SMYD5 inhibitor and chemotherapy may enhance the therapeutic effect of lung cancer treatment." (PMID 38723947, 2024). "Thus, we suggest that SMYD5 is involved in lung cancer metastasis via the critical regulation of SH2B3 expression." (PMID 38723947, 2024). "In this study, to identify the direct target by which SMYD5 facilitates lung cancer metastasis, we focused on 788 upregulated genes in the RNA-seq results after SMYD5 knockdown because SMYD5 mainly trimethylates H4K20 to repress gene expression via heterochromatin construction." (PMID 38723947, 2024). "Thus, to increase the efficiency of lung cancer treatment, SMYD5-specific inhibitors need to be developed." (PMID 38723947, 2024). "Thus, we suggest that direct targeting of SMYD5 with siRNA or specific inhibitors for the repression of lung cancer metastasis is an important strategy for lung cancer treatment." (PMID 38723947, 2024). "Therefore, targeting the activity or expression of SMYD5 using specific inhibitors or siRNAs to reduce cancer metastasis could enhance the effectiveness of lung cancer treatment." (PMID 38723947, 2024). "In this study, SMYD5 knockdown clearly suppressed TGF-β-induced migration and invasion of highly invasive lung cancer cell lines." (PMID 38723947, 2024). "Thus, SMYD5 may be an important regulator of lung cancer metastasis." (PMID 38723947, 2024). "Recently, we reported that SMYD2 knockdown reduced lung cancer metastasis in vitro and in vivo metastasis analyses, but similar to SMYD5 knockdown, SMYD2 knockdown did not affect cell growth inhibition in lung cancer cell lines." (PMID 38723947, 2024).
acute myeloid leukemia (2 papers, 2016 to 2025). Acute myeloid leukemia (AML) is a group of neoplasms arising from precursor cells committed to the myeloid cell-line differentiation. "NPM1 mutations are commonly observed (~30%) in acute myeloid leukemia (AML), suggesting that SMYD5 participates in myeloid cell differentiation/proliferation through its interaction with NPM1." (PMID 27377701, 2016).
lung adenocarcinoma (2 papers, 2024). A carcinoma that arises from the lung and is characterized by the presence of malignant glandular epithelial cells. "Specifically, SMYD5 exhibited a mutation frequency of 2.3% in colorectal cancer, while SMYD1 demonstrated a mutation frequency of 2.3% in both lung adenocarcinoma and lung squamous cell carcinoma." (PMID 38892284, 2024).
Arthritis (1 paper, 2025). Inflammation of a joint. "According to the Arthritis Index, SMYD5 knockdown delayed the onset and alleviated the severity of arthritis in CIA mice." (PMID 40165083, 2025). "Supporting these findings, intraarticular delivery of AAV-mediated SMYD5 knockdown in the CIA mice model effectively alleviated joint swelling, bone erosion, and overall arthritis severity." (PMID 40165083, 2025).
Cirrhosis (1 paper, 2024). A chronic disorder of the liver in which liver tissue becomes scarred and is partially replaced by regenerative nodules and fibrotic tissue resulting in loss of liver function. "Furthermore, the genetically engineered mouse model of cirrhosis-associated HCC with hepatocyte-specific Smyd5 KO indicated that the SMYD5-RPL40 K22me3 pathway is critical in tumor initiation and progression." (PMID 39103523, 2024). "To investigate the role of SMYD5 in HCC tumorigenesis from the cirrhosis stage, we interbred conditional Smyd5loxP/loxP mutant mice with hepatocyte-specific Cre-recombinase strain (AlbCre), resulting in specific Smyd5 gene deletion in the liver." (PMID 39103523, 2024).
endometrial carcinoma (1 paper, 2024). A malignant tumor arising from the epithelium that lines the cavity of the uterine body. "In endometrial carcinoma, the mutation frequencies were 3.3% for SMYD1, 2.1% for SMYD2, 2.1% for SMYD3, 2.1% for SMYD4, and 2.4% for SMYD5." (PMID 38892284, 2024).
gastric cancer (1 paper, 2025). A primary or metastatic malignant neoplasm involving the stomach. "Notably, SMYD5 has been implicated in the malignant progression of gastric cancer and LIHC by promoting the trimethylation of rpL40K22, which enhances mRNA translation output." (PMID 40872497, 2025). "Furthermore, inhibition of either SMYD5 or its substrate rpL40K22me3 has been shown to significantly reduce the metastasis of gastric cancer cells and increase sensitivity to PI3K-mTOR inhibitors in gastric cancer." (PMID 40872497, 2025).
inflammatory bowel disease (1 paper, 2025). A spectrum of small and large bowel inflammatory diseases of unknown etiology. "A few studies have reported that SMYD5 plays a crucial role as an epigenetic regulator in immune-related diseases, such as inflammatory bowel disease (IBD)." (PMID 40165083, 2025).
kidney chromophobe carcinoma (1 paper, 2025). "Conversely, patients with kidney chromophobe carcinoma (KICH) exhibited lower SMYD5 expression levels relative to normal individuals." (PMID 40872497, 2025).
liver cancer (1 paper, 2024). An epithelial or non-epithelial malignant neoplasm that arises from the liver. "The synthesis of primary bile acids influences SMYD5, and silencing its expression may impede liver cancer progression, suggesting another potential therapeutic avenue." (PMID 39428564, 2024).
osteoarthritis (1 paper, 2025). A noninflammatory degenerative joint disease occurring chiefly in older persons, characterized by degeneration of the articular cartilage, hypertrophy of bone at the margins and changes in the synovial membrane. "Proteomic screening was conducted to assess SMYD5 expression in the synovium of patients with osteoarthritis (OA) and RA." (PMID 40165083, 2025).
rheumatoid arthritis (1 paper, 2025). A chronic, systemic autoimmune disorder characterized by inflammation in the synovial membranes and articular surfaces. "This study aimed to investigate the role of SMYD5 in regulating synovial fibroblast homeostasis and the pathogenesis of rheumatoid arthritis (RA)." (PMID 40165083, 2025).
cancer (10 papers, 2016 to 2025). A tumor composed of atypical neoplastic, often pleomorphic cells that invade other tissues. "Specifically, SMYD5 catalyzes the trimethylation of histone H3 at lysine 36, which is associated with transcriptional activation in cancer." (PMID 40872497, 2025). "Elevated protein synthesis and translation activity are hallmarks of cancer, and SMYD5 is frequently overexpressed in HCC and associated with poor clinical outcomes." (PMID 39103523, 2024). "Although SMYD4 and SMYD5 have recently been associated with cancer, few studies have investigated these associations." (PMID 39482529, 2024). "Deficiency of SMYD5 in HCC cancer cells leads to hypersensitivity to mTOR inhibitors, likely due to a compounded inhibitory effect on protein synthesis." (PMID 39103523, 2024). "These elevated H3K36me3 may not only caused by SMYD5 but also SETD2 in cancer tissues." (PMID 35680905, 2022). "To explore the involvement of SMYD5 in cancers, we used the TIMER2.0 platform to assess its expression across 33 cancer types from the TCGA dataset." (PMID 40872497, 2025). "Pan-cancer analyses revealed a significant positive correlation between elevated SMYD5 expression and poor overall survival (OS) and disease-free survival (DFS) across multiple cancer types, with the strongest association observed in LIHC." (PMID 40872497, 2025). "In this study, we examined SMYD5 across multiple cancers, with a focus on LIHC, and investigated its interaction with BRD4 in LIHC progression." (PMID 40872497, 2025). "Recent studies have primarily focused on the role of SMYD5 as a ribosomal methyltransferase and its significance in cancer." (PMID 40872497, 2025). "Our SNU449 xenograft and PDX HCC models demonstrate that SMYD5 depletion alone significantly suppresses cancer growth, and renders them hypersensitive to mTOR suppression." (PMID 39103523, 2024). "SMYD4 and SMYD5 are involved in cellular processes that are relevant to cancer development and progression, including gene regulation and cell signaling." (PMID 39482529, 2024). "Employing both ex vivo and in vivo HCC models, we further elucidate the critical role of SMYD5-mediated RPL40 K22me3 in sustaining cancer growth, especially under suppressed mTOR signaling." (PMID 39103523, 2024). "To date, there are relatively few studies on the function of SMYD4 and SMYD5 in cancer, which necessitate further research." (PMID 36816359, 2023). "Furthermore, our pan-cancer analyses demonstrated a robust positive correlation between heightened SMYD5 levels and poor OS and DFS, especially among LIHC patients." (PMID 40872497, 2025). "Flow cytometry analysis showed that silencing SMYD5 increases the apoptosis rates, suggesting that SMYD5 may contribute to the resistance to programmed cell death, a common feature of cancer progression." (PMID 40872497, 2025). "This comprehensive analysis suggests that targeting SMYD5 may enhance immune responses against tumors, highlighting its potential as a therapeutic target in cancer immunotherapy." (PMID 40872497, 2025). "Given the immune system’s critical role in tumor regulation, targeting SMYD5 could enhance anti-tumor immunity and stand as a viable strategy in cancer immunotherapy." (PMID 40872497, 2025). "However, systematic pan-cancer analyses of SMYD5, particularly regarding its molecular mechanisms and epigenetic roles in tumorigenesis and progression, are still lacking." (PMID 40872497, 2025). "However, although SMYD5 is related to cancer progression and other biological processes, the functions of SMYD5 in cancer cell proliferation and metastasis are unclear." (PMID 38723947, 2024). "Importantly, since SMYD5 is also elevated in other cancer types (TCGA), future research should focus on developing specific inhibitors or modulators of SMYD5 as a general approach for cancer therapy." (PMID 39103523, 2024).
cancer (continued). "SMYD4 has been identified as a tumor suppressor gene in breast cancer, and SMYD5 may be involved in cancer and stem cell maintenance." (PMID 36816359, 2023). "Moreover, we analyzed the protein levels of SMYD5 and H3K36me3 in paired non-cancer and cancer tissues from eight patients." (PMID 35680905, 2022). "Furthermore, the therapeutic implications of targeting SMYD5 may provide novel avenues for enhancing the efficacy of existing cancer treatments." (PMID 39335515, 2024). "The number of studies on SMYD4 and SMYD5 in the field of cancer has increased, although relatively few reports have compared SMYD4 and SMYD5 to SMYD2 and SMYD3." (PMID 39482529, 2024). "Except one patient (patient #1) who had a lower molecular weight band of SMYD5 in non-cancer tissues, we detected an increase of SMYD5 in cancer tissues than non-cancer tissues." (PMID 35680905, 2022). "As shown in the heatmaps, the hsa_circ_0001495, miR-125b-5p, and GPM6A were down-regulated in cancer tissues compared to their paired para-carcinomal tissues of HCC, whereas hsa_circ_0000688, miR-106b-5p, and four mRNAs (UNKL, GPRIN1, SMYD5, AURKB) were up-regulated." (PMID 35002514, 2022).